PPP1R14B (protein phosphatase 1 regulatory inhibitor subunit 14B)
Description:
Inhibitor of PPP1CA. Has over 50-fold higher inhibitory activity when phosphorylated (By similarity).
Synonyms: PLCB3N; PNG; SOM172; PHI-1
Tractability: PROTAC: ubiquitination databases record sites on it; its protein half-life has been measured.
Gene: Protein-coding gene on chromosome 11 (64,244,478 to 64,246,943, reverse strand). Ensembl gene ENSG00000173457.
Subcellular location: Cytoplasm
Gene Ontology:
Molecular function: protein binding; protein serine/threonine phosphatase inhibitor activity; phosphatase inhibitor activity; protein phosphatase regulator activity
Biological process: innate immune response
Cellular component: cytoplasm
Genetic constraint (gnomAD): Loss-of-function variants: 4 observed, 14 expected, observed/expected ratio (o/e) 0.29, 90% interval 0.14 to 0.65. The upper end of that interval is the gene's LOEUF score, 0.65, which puts it in group 2 of 6, group 1 being the genes least tolerant of losing a copy. Missense variants: 138 observed, 174.46 expected, observed/expected ratio (o/e) 0.79, 90% interval 0.69 to 0.91. Synonymous variants: 76 observed, 73.5 expected, observed/expected ratio (o/e) 1.03, 90% interval 0.86 to 1.25.
Homologues: Orthologues: macaque PPP1R14B (100% identical), pig PPP1R14B (83% identical), mouse Ppp1r14bl (75% identical), rat Ppp1r14bl (72% identical), tropical clawed frog ppp1r14b (69% identical), zebrafish ppp1r14bb (63% identical), guinea pig PPP1R14B (61% identical), zebrafish ppp1r14ba (57% identical), Drosophila melanogaster CG17124 (27% identical), Caenorhabditis elegans F55C10.5 (20% identical). Paralogues in human: PPP1R14C (59% identical), PPP1R14A (34% identical), PPP1R14D (30% identical).